MITF (melanocyte inducing transcription factor)
Diseases named in the same sentence as MITF in open-access papers (continued):
Sharing a sentence is not in itself a finding about the gene and the disease.
melanoma (continued). "In summary, the MAPK-pathway has stringent control over the melanocyte/melanoma fate-decision regulator MITF, which might explain why this pathway is so particularly critical in the biology of a melanocytic cell and hence in melanoma." (PMID 27200346, 2016). "This oscillatory regulation of MiTF expression is a critical determinant of melanoma metastasis development and could account for melanoma heterogeneity, plasticity and drug resistance." (PMID 27827420, 2016). "On the contrary, high MITF expression levels can slow down the proliferation of melanoma cells." (PMID 26927636, 2016). "In both cases (particularly for MITF-deficient melanoma cells) RAB27A levels were reduced in the absence of CPEB4." (PMID 27857118, 2016). "As MITF is listed among attractive therapeutic targets in melanoma, the pentoxifylline-driven downregulation of its expression and activity might have important clinical implications." (PMID 27351373, 2016). "Thus, induction of senescence was accompanied by MITF-M depletion only in MITF-Mhigh melanoma cells." (PMID 26824319, 2016). "We thus investigated whether the sensitivity of 28 BRAFV600‐mutated melanoma cell lines from the CCLE to BRAFi and MEKi was correlated with their EMT‐TF/MITF expression profiles." (PMID 27596438, 2016). "Amplification of MITF is observed in 10% of primary and in 15–20% of metastatic melanomas and so it may be considered an oncogene in melanoma." (PMID 26863566, 2016). "Additionally, we found that SOX5 knockdown led to MITF up-regulation in melanoma cells, while double knockdown with SOX10 showed a rescue effect; both effects were validated by reporter assays." (PMID 26927636, 2016). "Interestingly, depletion assays demonstrated that the requirement of CPEB4 to maintain MITF levels was also found to extend to normal melanocytes, the cells or origin of melanomas." (PMID 27857118, 2016). "To investigate the role of SOX10, MITF, and FOXD3 and the reported effects due to BRAF status in ERBB3 regulation, we depleted the three former genes individually and in combination for MITF/FOXD3 by the use of siRNA in three melanoma cell lines: WM983B, MeWo and WM115." (PMID 27391157, 2016). "Indeed, the depletion of MITF from MITF-expressing NRAS mutant melanoma cells significantly sensitized these cells to MEK inhibition." (PMID 26977879, 2016). "Melanoma cells expressing MITF at high level can either differentiate or proliferate." (PMID 25433395, 2015). "MCL-1 dependence seems to be especially important in melanoma populations with high MITF level and activity, whereas in populations in which MITF is expressed at low levels, BCL-XL may be sequentially involved after MCL-1 expression is reduced." (PMID 26035829, 2015). "Hence, possibly as the result of the accumulation of methylation events over time, individual melanoma cells become in fact locked in a relatively stable ‘MITF/differentiation‐off’ state." (PMID 25818589, 2015). "Lauss and colleagues have recently shown that MITF expression in melanomas is controlled by DNA methylation, but unfortunately RNA was unavailable to investigate whether the low DNA methylation changes here detected would impact MITF expression." (PMID 26106605, 2015). "In this model, expressions of AXL and WNT5A define a distinct MITF‐negative population of melanoma cells, where MITF expression is not linked to BRN2 and the MAPK pathway and cells are MAPK pathway inhibitor unresponsive." (PMID 25818589, 2015). "MITF can be regulated by various pathways; this might explain why the role of MITF in melanoma progression is still unclear." (PMID 26393652, 2015). "We have also checked whether MITF and ERK-1/2 were involved in adaptive melanoma cell response as both MITF expression and ERK-1/2 activity clearly differ between cells continuously cultured in either of tested medium." (PMID 26035829, 2015). "In this study, we characterise the role of CITED1 as a novel regulator of MITF in melanoma." (PMID 25755924, 2015).
melanoma (continued). "Importantly, TGFβ treatment leads also to a significant reduction in PAX3 and MITF expression in melanoma cells and this correlates with the growth suppressor activity of this cytokine." (PMID 25818589, 2015). "Re-analysis of the gene expression data from our TNF-stimulated melanoma cell line panel consistently revealed that suppression of MITF mRNA significantly correlated with the reciprocal induction of c-JUN mRNA, but obviously this switch was variable among the different cell lines." (PMID 26530832, 2015). "This may protect the MITF-driven proliferative cell state in melanoma cells against transient inflammatory changes in the tumour microenvironment." (PMID 26530832, 2015). "However, melanoma patients harboring high levels of MITF have fewer metastases, suggesting that the regulation of MITF by diverse signaling pathways can have a distinct effect on melanoma cells." (PMID 26393652, 2015). "Microphthalmia-associated transcription factor (MITF), a basic helix-loop-helix leucine zipper (bHLH-Zip) factor, regulates specification, survival, and proliferation of normal melanocytes, and controls proliferation, migration and invasion of melanoma cells." (PMID 25803486, 2015). "Indeed, we have previously shown that AXL is highly expressed, at the protein level, in human melanoma cell lines and clinical samples which lacks expression of MITF and of MITF-targets." (PMID 25742786, 2015). "We consequentially hypothesized that the antagonistic interrelationship between MITF and c-Jun represents an important determinant for the reciprocal cross-talk of melanoma and immune cells in the tumour microenvironment." (PMID 26530832, 2015). "In melanoma, constitutive activation of ERK – mainly, stimulated by oncogenic activation of upstream MAPK components – is associated with a marked degradation of MITF." (PMID 26322273, 2015). "This suggests strikingly opposing functions of β‐catenin in early and late stages of melanoma development, but so far, the role of MITF downstream of mutant β‐catenin particularly in the stages of metastasis is unknown." (PMID 25818589, 2015). "Indeed, MITF is essential for the maintenance of oncogenic BRAF‐driven melanoma in vivo, and the level of MAPK pathway activation appears to be critical for MITF abundance and function in melanoma cells." (PMID 25818589, 2015). "We previously reported a genome wide analysis of MITF target genes in 501Mel melanoma cells." (PMID 25803486, 2015). "M‐MITF (for simplicity called MITF in this review) is expressed in >80% of melanomas and detectable throughout all stages of melanoma development, although the conclusions regarding an overall increase or decrease in MITF expression levels during melanoma progression are controversial." (PMID 25818589, 2015). "Regulation by TNF‐α can induce MITF expression in melanoma cells through IKK/NFkB signalling." (PMID 25818589, 2015). "The evidence of the tight control exerted over MITF levels in melanocytes and melanoma simply speaks to the necessity of the cell to maintain a level compatible with survival and proliferation, in a type of biological ‘sweet-spot’ facilitating tumour progression." (PMID 25755924, 2015). "MITF can control melanoma cell differentiation and proliferation through cell cycle arrest." (PMID 25763355, 2015). "If epigenetic switching with regard to MITF expression is a rare event during melanoma progression, additional processes might contribute to the maintenance of heterogeneity with regard to MITF‐positive and MITF‐negative populations." (PMID 25818589, 2015). "However, our data indicate that in melanoma cells deficient in CDKN1A/P21, the alternative CDK inhibitor CDKN1C/P57 is expressed and responsive to MITF." (PMID 25755924, 2015).
melanoma (continued). "Hypermethylation of the MITF promoter was detected in peripheral blood of those melanoma patients who developed more than one lesion (multiple primary melanomas), and MITF gene body was found to be somehow hypermethylated in primary tumors compared to metastasis." (PMID 26106605, 2015). "Analogous results were observed in several other MITF-expressing melanoma cell lines." (PMID 26440048, 2015). "Hence, the antagonistic relationship between MITF and c-Jun represents a species-conserved molecular framework governing melanoma cell plasticity in response to inflammation." (PMID 26530832, 2015). "We found that MITF and c-Jun transcriptionally repress each other and therefore c-Jun induction by TNF-α instigates a feed-forward loop of melanoma dedifferentiation through MITF loss that is mechanistically linked to increased cytokine responsiveness caused by accumulation of c-Jun." (PMID 26530832, 2015). "Acting as a cofactor for MITF is therefore only one facet of BPTF function in melanoma cells." (PMID 26440048, 2015). "Thus, constitutive activation of the oncogenic mutant BRAFV600E, occurring in 50% of melanomas, represses the MITF/PGC-1α axis and, in turn, lowers mitochondrial OXPHOS." (PMID 26713093, 2015). "MITF, a melanocyte-specific modulator also recognized as a lineage addiction oncogene in melanoma, has been described as regulating expression of anti-apoptotic and stress-attenuating genes in melanocytes and melanoma cells." (PMID 26035829, 2015). "Altogether, these results demonstrate that patient-derived melanoma populations cultured in EGF(+)bFGF(+) medium may markedly differ in expression of MITF and MITF-dependent genes, but also in regard to the baseline pro-survival machinery." (PMID 26035829, 2015). "For instance, an MITF gene amplification is found in ~20% of metastatic melanomas." (PMID 25818589, 2015). "In contrast, MITF represses genes involved in melanoma invasion." (PMID 25803486, 2015). "The function of MITF in melanoma development is complex, which is partly due to its dynamic regulation, for example through the genetically activated ERK/MAPK pathway in addition to microenvironment‐derived signalling, but also due to its broad range of target genes." (PMID 25818589, 2015). "We hypothesized that prolonged TNF-α exposure (72 h) steadily increases c-JUN mRNA and protein expression through reduction of MITF and thereby progressively amplifies inflammatory gene programmes in melanoma cells." (PMID 26530832, 2015). "MIcrophthalmia-associated Transcription Factor (MITF) regulates melanocyte and melanoma physiology." (PMID 26440048, 2015). "Furthermore, the ablation of functional MITF expression in BRAFV600E induced melanomas in zebrafish leads to tumour regression." (PMID 25818589, 2015). "Alternative splicing is another mechanism of MITF regulation in melanoma." (PMID 25433395, 2015). "SOX10 is a lineage‐specific transcription factor that strongly activates the MITF promoter, and is crucial for MITF expression; accordingly, it is required for melanoma cell survival." (PMID 25818589, 2015). "Furthermore, the regulation of MITF expression and function is strongly linked to the BRAF/MEK/ERK/MAP‐kinase (MAPK) pathway, which is deregulated in >90% of melanomas and central target of current therapies." (PMID 25818589, 2015). "Moreover, the authors showed that forced expression of MITF reduced EGFR signaling in melanoma and colon cancer cells, which restored sensitivity to BRAFi/MEKi." (PMID 26393652, 2015). "BCL2 is a MITF target gene involved in melanocyte and melanoma cell proliferation and survival." (PMID 26116372, 2015). "Indeed, increased MITF and PGC1α expression is found in patients with acquired resistance, but mTORC1/2 inhibition can overcome PGC1α upregulation in melanoma cells, rendering them sensitive to MEK inhibition." (PMID 25818589, 2015).
melanoma (continued). "Interestingly, MITF expression was reported as variable among melanoma specimens and even intratumor, with high expression levels being associated with either differentiation or proliferation while low expression is related to an invasive potential." (PMID 26106605, 2015). "Enforced expression of MITF in immortalized melanocytes or neural crest progenitor cells when introduced together with melanoma-specific BRAFV600E suggests MITF’s role as a melanoma addiction oncogene." (PMID 25433395, 2015). "Interestingly, MITF-positive cells are also found at metastatic sites, suggesting an ability of melanoma cells to switch back and forth between these transcriptional states." (PMID 25865119, 2015). "Moreover, melanoma cell clusters circulating in patient blood were shown to express MITF heterogeneously." (PMID 25066122, 2014). "ZEB1 may drive a failsafe program for a melanoma cell to overcome the senescent state, exemplifying why ZEB1 expression in human melanoma is inversely correlated with MITF status." (PMID 25538895, 2014). "Hence, MITF plays a critical role in melanocyte development and functioning but it is also considered a bona fide melanoma oncogene." (PMID 24742694, 2014). "FOXD3 was reported to inhibit MITF expression, and therefore might participate to the maintenance of the melanoma initiating cell phenotype." (PMID 25105565, 2014). "MITF also functions downstream the PI3 kinase pathway that is also deregulated in melanoma." (PMID 25105565, 2014). "Moreover, SIRT1 overexpression relieves the senescence-like phenotype and the proliferation arrest caused by MITF knock-down, thereby demonstrating that SIRT1 is an effector of MITF-induced proliferation in melanoma cells." (PMID 24742694, 2014). "Indeed, over expression of MITF in human melanoma cells increase the expression of ABCB5 and ChIP experiment showed that MITF binds to the ABCB5 gene." (PMID 25105565, 2014). "In melanoma, phenotype switching is thought to follow altered MITF expression." (PMID 25066122, 2014). "Furthermore, MITF is downstream the MAP Kinase pathway that is frequently deregulated in melanoma, due to BRAFV600E mutation." (PMID 25105565, 2014). "Therefore MITF, which is recurrently targeted by oncogenic events in melanomas, is the perfect candidate to regulate the transition between melanoma initiating cells and their more differentiated progeny." (PMID 25105565, 2014). "Interestingly, MITF is an oncogene in melanoma, and leads to cell survival via upregulation of BCL2 and other molecules." (PMID 24827933, 2014). "Indeed, transient inhibition of MITF expression, which is considered as a melanoma oncogene, blocks melanoma cell growth in vitro, but counter-intuitively favors xenograft and metastasis development in nude mice." (PMID 25105565, 2014). "This EMT-TF reprogramming is followed by the reduction in the expression of MITF which may lead to the establishment of functional divergent melanoma cell populations based on the “rheostat model”." (PMID 25051363, 2014). "High MITF expression protected melanoma cells against MEK inhibitor cytotoxicity." (PMID 24743024, 2014). "Although the role of HMGA2 in melanoma invasiveness is unknown, TGF-β/GLI2 and MITF inversely regulate invasion and pigmentation in melanoma cells, which is consistent with the present results." (PMID 24733089, 2014). "Interestingly, it has been demonstrated that agents increasing MITF expression can be exploited in anti-melanoma therapeutic strategies." (PMID 24595456, 2014). "In melanoma, Axl is associated with NRAS mutations compared to BRAF mutations, and is inversely correlated with the expression of the microphthalmia-associated transcription factor (MITF)." (PMID 25344858, 2014). "Therefore, we studied the effect of the secretome of melanoma cells rendered senescent by MITF silencing on these markers." (PMID 24344100, 2013).
melanoma (continued). "Therefore, the CDK inhibitor P27 is increased in MITF-depleted cells and is required for exacerbation of the tumorigenic properties of melanoma cells." (PMID 23762150, 2013). "Likewise, several studies indicate that MITF can promote melanocyte and melanoma survival following UV radiation." (PMID 23480510, 2013). "We recently profiled global gene expression in a panel of 25 of these cell lines, and showed that NZM and other melanoma cell lines could be classified into two major groups represented by relatively lower (6/25) or higher (19/25) MITF transcript levels." (PMID 24062982, 2013). "Several molecular strategies have been investigated that may alter expression or activity of MITF within melanocytes or melanoma cells." (PMID 24157419, 2013). "Moreover, the morphological effects of knocking down PAX3 versus MITF in melanoma cells were found to differ." (PMID 24062982, 2013). "Here we extend a hypothesis that we previously suggested; that PAX3 and MITF play independent roles in melanoma progression." (PMID 24062982, 2013). "High expression of POU3F2 in melanoma represseses MITF expression." (PMID 24062982, 2013). "Although cyclin dependent kinase (CDK)-2 is known to be dispensable for the growth of most tumors, it is thought to be important for the proliferation of melanoma cells, where its expression is controlled by the melanocyte-lineage specific transcription factor MITF." (PMID 23527225, 2013). "There are speculations as to what could induce or decrease MITF activity and determine the invasiveness or the stemness of the melanoma cells in response to hypoxia or to other factors in the tumor microenvironment." (PMID 23755070, 2013). "Furthermore, we show that knockdown of PAX3 inhibits cell migration in a group of “lower MITF” melanoma cell lines, while knockdown of MITF promotes cell migration in a complementary “higher MITF” group of melanoma cell lines." (PMID 24062982, 2013). "Together these results demonstrate an essential role of SWI/SNF for the expression of MITF-dependent and MITF-independent prosurvival factors in melanoma cells and suggest that SWI/SNF may be a potential and effective target in melanoma therapy." (PMID 23349796, 2013). "We next investigated whether expression of PAX3 is associated with loss of growth control in melanoma, which is a role that MITF has been implicated, as might be expected if PAX3 and MITF were to function in the same or similar pathways." (PMID 24062982, 2013). "Like CSCs, the expression of melanogenic molecules, such as Wnt/β-catenin, c-Kit, and MITF, in melanoma exhibits strong morphological, functional, and molecular heterogeneity that might reflect the existence of different cancer cell populations." (PMID 23762150, 2013). "In human melanoma cell lines, many MITF targets require the SWI/SNF complex for expression." (PMID 23349796, 2013). "Therefore, it will be crucial to more precisely define the role of MITF and miR-211 in order to consolidate the true relevance of this microRNA for melanoma cell invasion." (PMID 24039954, 2013). "MITF has been suggested to be an important melanoma growth and survival factor." (PMID 24062982, 2013). "The present study stimulated melanoma B16 cells with α-MSH and demonstrated the increased expression of melanin production to be accompanied with the upregulation of CSC-associated molecules (Wnt-1/β-catenin, c-Kit, MITF, and MMP-9) and invasion ability." (PMID 23762150, 2013). "It was reasoned that this negative feedback loop on MITF, enforced by the loss of miR-211, would keep melanoma cells in a de-differentiated, pro-invasive state." (PMID 24039954, 2013). "Thus, in melanoma cells, miR-182 modulate the expression of both FOXO3 and microphthalmia-associated transcription factor (MITF)." (PMID 32309538, 2013).